IL10 (interleukin 10)
Diseases named in the same sentence as IL10 in open-access papers (continued):
Sharing a sentence is not in itself a finding about the gene and the disease.
malaria (continued). "Our data demonstrate the first evidence that polymorphisms in IL17 may be associated with uncomplicated malaria in the Cameroonian population while SNPs in, IL10, IL17RD, IRF1, TLR1and TLR9 may be linked with severe malaria in general." (PMID 24312262, 2013). "Elevated levels of anti-inflammatory IL-10 have previously been reported in severe malaria." (PMID 23630573, 2013). "High levels of IL-10 observed during malaria episodes may be beneficial in reducing the inflammatory response, but it may also be detrimental by decreasing antiparasitic cellular immune responses." (PMID 23533445, 2013). "Our data demonstrate the first evidence that polymorphisms inIL17 may be associated with uncomplicated malaria in the Cameroonian population while SNPs in, IL10 IL17RD, IRF1, TLR1 and TLR9 may be linked with severe malaria." (PMID 24312262, 2013). "This suggests that rs1800890 may act to upregulate IL10 transcription, with the heterozygotes providing some selective advantage since the raised IL10 levels will down-regulate proinflammatory cytokines such as TNFα and protect against severe malaria." (PMID 24312262, 2013). "Travelers and immigrants with malaria also had higher levels of IL-10 (325.68 [52.71; 740.19] pg/mL and 210.1 [65.55, 1277.3] pg/mL, respectively) compared to individuals with other diseases (7.7 [0.95, 11.47] pg/mL, 325.68 [52.71, 740.19] pg/mL, respectively, P<0.0001)." (PMID 23967342, 2013). "Several studies have demonstrated that the imbalance of pro- and anti-inflammatory cytokines is associated with the immuno-pathogenesis of severe malaria anaemia (SMA) and cerebral malaria (CM) with Tumor necrosis factor (TNFα) and interleukin-10 (IL10) critical in this role." (PMID 24312262, 2013). "Thus observation is consistent with a model in which interferon-γ and IL-10 secreting T cells play important roles in host immune response against malaria." (PMID 24188121, 2013). "All malaria patients produced higher IL-10 absolute levels than AC (P ≤ .0038)." (PMID 22853732, 2012). "In particular, intracellular IFN-γ and IL-10 production by CD3+ cells was associated with higher incidence of malaria during the first year of age but not in the second year." (PMID 22280502, 2012). "No study has reported the expression of NF-κB in PBMCs from malaria patients and its association with circulating cytokines such as IL-10 and TNF." (PMID 22682094, 2012). "IL-10 is a key cytokine both in the protection and in the pathogenesis of malaria." (PMID 23155405, 2012). "To investigate a potential role for UA in malaria pathogenesis, we first measured the levels of ten cytokines (IL-6, IL-10, MCP-1, sTNFRII, IL-8, IP-10, TNFα, IFNγ, GM-CSF and IL-1β) that other studies have implicated in the development of severe malaria in humans." (PMID 23071567, 2012). "Highly elevated levels of cytokines primarily produced by macrophages and dendritic cells (IL-6, MCP-1, TNF-α, IL-10) in M. tuberculosis-PbNK65 co-infected animals indicate that immune regulation is significantly impaired when malaria is concurrent with tuberculosis in mice." (PMID 23110184, 2012). "Further work to investigate whether pre-incubation of the malaria sera with an anti-IL-10 neutralizing monoclonal antibody would suppress NF-κB activation in PBMCs from complicated P. falciparum patients will be of interest." (PMID 22682094, 2012). "Understanding how these non-classical regulatory cells are induced could help to explain species-related differences in IL-10 production in human malaria." (PMID 22973442, 2012). "Elevated IL-10 levels have been detected in serum of Thai patients with acute P. falciparum malaria prior to treatment and the levels were found to return to normal after malaria treatment." (PMID 22682094, 2012).
malaria (continued). "In selected experiments we examined TGF-β and IL-10 intracellular production after malaria and schistosomal antigen stimulation in PBMC obtained from 8 SP children (4 SP Mal and 4 SP no Mal) and 6 SN Mal children with malaria, during the wet and dry season follow-up." (PMID 22348117, 2012). "This indicates that IL-10 has an important regulatory role in malaria infection, controlling the intensity of the immune response, as has been described in malaria experimental model and human malaria and in a number of other infectious diseases." (PMID 21917128, 2011). "Both IFN-γ and IL-10 responses were more prevalent in subjects who had malaria-specific antibodies and/or memory B cells suggesting – unsurprisingly, perhaps - that the three arms of the adaptive immune response (cellular, humoral and regulatory) are induced in a coordinated fashion." (PMID 21347351, 2011). "Additionally, the cytokine balance seems to be linked to disease severity, as individuals with asymptomatic malaria presented a reduced IFN- γ/IL-10 ratio." (PMID 21625634, 2011). "However, other factors in addition to cytokine profile must be involved in the reduced malaria severity in individuals with HBV, as the risk for asymptomatic infection was even higher when we analyzed the adjustment for plasma IL-10 and IFN-γ levels." (PMID 21625634, 2011). "However, IL-10 has also been shown to induce hemoxygenase-1 (HO-1), an inflammatory mediator in severe malaria, detected on immunohistochemical stain at autopsy in the brains of children with cerebral malaria and sequestration." (PMID 21447146, 2011). "One speculates that high levels of the Th2 cytokines (IL-10) during helminth infection counteract the Th1 cytokines (TNF) induced by malaria to prevent the development of severe anemia." (PMID 20574512, 2010). "Magnesium deficiency, on the other hand, was associated with increased concentrations of IL-10; this increase was 46% in children without malaria, as compared to only 6% in their peers with malaria." (PMID 20470442, 2010). "In this study that was carried on the coast of Kenya, authors also report an increase in IL-10 serum mRNA expressions in malaria blood-smear positive children, results which are concordant with our in vitro results on iron deficiency anaemia despite the weak evidence." (PMID 20546583, 2010). "IL-10 is a key cytokine involved in both protection and immunopathology during malaria." (PMID 20706538, 2010). "For instance, mice infected with the malaria parasite Plasmodium chabaudii and whose IL-10 was experimentally neutralized experienced shorter time to death compared to infected/IL-10+ controls, showing that immunopathology substantially contributes to the overall cost of infection in this system." (PMID 20886083, 2010). "There may also be different roles for the major regulatory molecules produced by Treg cells in our study (CTLA-4) and inducible regulatory T cells identified by others (IL-10;), by acting on different cellular/tissue targets during malaria." (PMID 21170302, 2010). "A role for IL-10-producing inducible regulatory T cells and/or IL-10/IFNγ-producing Th1 cells identified in P. yoelii-infected mice and malaria patients, respectively, may also contribute to this latter process." (PMID 21170302, 2010). "At age 6 months, the T cells of exposed, not-sensitized children were less likely to make activating cytokines in response to malaria antigens but made more IL-10 than the T cells of the other children; malaria-specific antibody levels were similar in the three groups." (PMID 19636353, 2009). "In summary, putatively tolerant newborns have an impaired malaria-specific Th1-type cytokine response, a reciprocal increase in antigen-driven IL-10 production, and a similar Th2-type cytokine release, when compared to other children, and these differences persist through early childhood." (PMID 19636353, 2009).
malaria (continued). "In this context it was recently shown that effector T cells co-producing IFNγ and IL-10, which are more prevalent in children with mild than severe malaria, may help to regulate acute malarial inflammation." (PMID 19680449, 2009). "To conclude, it is known that long-term exposure to malaria causes chronic enlargement of the liver and the spleen and here the levels of three cytokines, IL-12p70, IL-10 and IL-13, and levels of sTNF-RII were found to be associated with both hepatosplenomegaly and exposure to malaria." (PMID 19149774, 2009). "IL-10 is a crucial immunoregulatory cytokine in both human and murine malaria; we have recently identified CD4+ T effector cells as a major source of IL-10, but the source of IL-10 in human malaria infection is unknown." (PMID 19343213, 2009). "IL-10 is a key cytokine both in protection and immunopathology during malaria." (PMID 18230163, 2008). "Plasma IgE levels correlated with those of IL-10 in uncomplicated malaria patients from Gabon." (PMID 17204149, 2007). "Whether IFNγ, TNFα and IL-10 regulate the self-reactive antibody response during malaria, as is the case for primary biliary cirrhosis, remains to be shown." (PMID 17460756, 2007). "Severe malaria has been associated with high TNF-α plasma levels in conjunction with increased production of IFN-γ and IL-1β and decreased production of anti-inflammatory cytokines, notably IL-10 and TGF-β." (PMID 17997848, 2007). "However, when IL-21 is included during the 6 days of culture, followed by a short incubation with IL-12, we found significantly greater IL-10 secretion from NK cells from individuals naive to malaria (malaria-naive) and those with a history of malaria (malaria-experienced)." (PMID 40337867, 2025). "Together, these data show that classical monocyte responses to malaria parasites in naive individuals are influenced by age, with adults having a focused inflammatory response while, children had a polyfunctional monocyte cytokine response with higher IL10+ frequencies." (PMID 41027884, 2025). "As a result, pregnant women with a history of malaria had high levels of all evaluated cytokines when compared to pregnant women without prior exposure to the parasite; this increase was more relevant among the cytokines IL-6, IL-8, IL-10 and TNF-α (respectively)." (PMID 39495782, 2024). "The exciting finding of higher level of IL-10 suggests that this cytokine may be responsible for the less inflammation, less pathology, and better prognosis seen in children with uncomplicated malaria compared to complicated malaria." (PMID 39039450, 2024). "This suggests that rs1800890 may upregulate IL-10 transcription, with the heterozygotes potentially providing a selective advantage, as elevated IL-10 levels can down-regulate proinflammatory cytokines such as TNFα, offering protection against severe malaria." (PMID 38404582, 2024). "For instance, the host cells elaborate IFN-γ, TNF-α, and IL-10 following exposure to malarial parasites and the increase in production of these cytokines contribute to the expression of the adhesion molecules often seen in patients with complicated and uncomplicated malaria." (PMID 39039450, 2024). "IL-10 production by B cells is indicative of Breg subsets, which have been shown in mice to be a major source of IL-10 during experimental malaria infection, and protect from experimental cerebral malaria, however have yet to be identified during human malaria." (PMID 37968278, 2023). "Indeed, during infection B cells were a major contributor of IL-10 from lymphocytes during malaria." (PMID 37968278, 2023). "Also a decreased risk of clinical malaria once infected has been associated with the frequency of CD4 T cells producing IL-10 but not inflammatory cytokine like IFN-γ." (PMID 36787308, 2023). "Hence, alterations in the anti-inflammatory cytokine IL-10 may diminish the uncontrolled immune responses and contribute to the pathogenesis of severe malaria." (PMID 36668942, 2023).
malaria (continued). "Here, we identified molecular and phenotypic signatures that distinguished IL-10–Th1 cells from IL-10+Tr1 cells in Plasmodium falciparum–infected people who participated in controlled human malaria infection studies, as well as C57BL/6 mice with experimental malaria caused by P. berghei ANKA." (PMID 36594463, 2023). "Furthermore, in both types of malaria (severe and uncomplicated), Gal-9 levels were associated with various pro- and anti-inflammatory cytokines and chemokines, including TNF, IL-6, IFN-α2, IFN-γ, IL-1Ra, and IL-10." (PMID 38067100, 2023). "Another possible explanation for elevated IL10 levels may be co-infection with other chronic parasitic infections, since plasma IL10 levels were found to be elevated in Schistosoma haematobium coinfection with malaria." (PMID 38033168, 2023). "This work suggests that the immunosuppressive activity of testosterone in malaria is mediated, at least in part, by IL-10, making it important to study the effects of testosterone on B lymphocytes, considering that the impact of the hormone on this cell population in malaria is unknown." (PMID 36237427, 2022). "Children repeatedly exposed to malaria in endemic settings develop a substantial proportion of antigen-specific IL-10+IFN-γ+ CD4+ T cells, prompting the question whether Tr1-mediated tolerance may contribute to the development of clinical immunity to Plasmodium infections." (PMID 36389662, 2022). "Indeed, interleukin (IL)-10 was shown to be a predictor of the occurrence of clinical malaria in highly endemic areas of India, while IL-6, IL-10 and IL-12 were associated with disease outcome in a non-endemic region." (PMID 35421083, 2022). "The IL-10/IL-6 ratio tended to be higher in those with P. falciparum infections alone (2.0 [0.9–3.6]) and 2-fold (2.5 [1.8–4.7]) and 3-fold (3.6 [2.0–11.9]) higher in those with dual infections with malaria/filariae and malaria/intestinal protozoans, respectively." (PMID 35421083, 2022). "Thus, our data highlight how IL-10 may distinctly govern humoral immunity during Plasmodium infection and further identify potential opportunities to improve durable immunity against malaria." (PMID 33529242, 2021). "Together, our data reveal temporal features and mechanisms by which IL-10 critically supports humoral immunity during blood-stage Plasmodium infection, information that may be useful for developing new strategies designed to lessen the burden of malaria." (PMID 33529242, 2021). "Indeed, defects in the production of TGF-β (TGFB1) and IL10, two anti-inflammatory factors, are associated with acute, severe malaria, severe malaria anemia, and an overall negative outcome." (PMID 33123155, 2020). "Therefore, an increased level of IL-10 secreted by B10 cells may lead to a decline of long-term protection by malaria ITV." (PMID 32257991, 2020). "IL-10 is a regulatory molecule in malaria, which could prevent excessive inflammation." (PMID 32599864, 2020). "We will highlight recent advances in our understanding about how IL-10 production by specific immune cell subsets is regulated and consider how this knowledge may be used in drug delivery and vaccination strategies to help eliminate malaria." (PMID 30809232, 2019). "Hence, IL-10 may be beneficial for the development of humoral immunity, but detrimental for cell-mediated immune responses during malaria." (PMID 30809232, 2019). "Therefore, modulation of IL-10 production in malaria may be achieved by targeting the activities of upstream activating cytokines, such as IL-27, IL-21, type I IFNs, TNF, or TGFβ." (PMID 30809232, 2019). "The timely regulation by anti-inflammatory cytokines such as IL-10, IL-4, and IL-13 to control the production and possible cytopathic effects of proinflammatory cytokines, plays a major role in limiting the progression of the uncomplicated malaria into its severe forms." (PMID 31110658, 2019). "Thus, IL-27 is a critical regulator of IL-10 producing Tr1 cells in mouse models of malaria." (PMID 30809232, 2019).
malaria (continued). "Thus, we believe that APRIL, BAFF, and IL‐10 production might be upregulated as a homeostatic response to the lymphopenia observed in the acute phase of malaria." (PMID 29314720, 2018). "Furthermore, increased IL-10 but not IL-12 production has been associated with increased parasite density in Mozambican children with both severe and uncomplicated malaria." (PMID 29970128, 2018). "In malaria, polyclonal B‐cell activation has been shown in the acute phase of P. vivax and P. falciparum malaria 15, which decreases 5–15 days after the beginning of treatment 15, with similar transient kinetics of IL‐10, APRIL and/or BAFF levels, observed in our study." (PMID 29314720, 2018). "Although high levels of IL-10 may play a beneficial role in human malaria by inhibiting parasite-induced pro-inflammatory responses that contribute to disease severity, studies have reported that high levels may also impair malaria clearance." (PMID 29137631, 2017). "However, the function of IL-10 in malaria is still unclear as IL-10 producing CD4+ T cells were involved in dampening severe pathology during Plasmodium infection whereas, it had also been reported to reduce levels of IFN-γ and TNF-α, which helps the parasites to escape the immune response." (PMID 28830553, 2017). "However, similarly to Treg in malaria, the role of IL-10-secreting B cells in infection could also consist in limiting the inflammatory reaction to the infecting microbe." (PMID 29403470, 2017). "However, the frequency of CD4 cells producing IL10 but not inflammatory cytokines (IFNγ and TNFα) was associated with a decreased risk of clinical malaria once infected." (PMID 29097996, 2017). "Moreover, IL-10, a key cytokine in malaria immunity, is a negative regulator of Th1 responses." (PMID 28583115, 2017). "Consequently, it is probable that IL-10–producing CD4+ T cells may only be effectively maintained in the presence of malaria Ag in context of TCR engagement." (PMID 27630165, 2016). "The categorical analysis of plasmatic cytokine indicated that regardless their clinical status, all malaria patients presented a typical cytokine storm and also pointed out that patients with recurrent malaria group exhibited enhanced proportion of subjects with high IL-10 levels." (PMID 27581163, 2016). "Finally, this global analysis allowed for verifying that recurrent malaria is associated with a particular biomarker profile, characterized by decreased levels of the CD4+ and CD8+ T-cells along with a significant increase in the IL-10 production." (PMID 27581163, 2016). "However, when these participants developed an acute episode of malaria, IL-6 and IL-10 cytokines increased considerably in all groups, but to a higher extent in subjects who were free of schistosome infection, which would suggest that S. haematobium impedes the cytokine storm." (PMID 25890010, 2015). "However, when assessed in a multivariate model, the frequency of malaria-specific IFNγ/IL-10 co-producing CD4+ T cells remained strongly associated with the duration since malaria, whereas the total prior incidence was no longer significant." (PMID 24415936, 2014). "Thus IL-10-induced suppression of neutrophil recruitment and macrophage function likely synergize with this neutrophil defect to increase susceptibility to disseminated NTS infection in the setting of malaria." (PMID 24787713, 2014). "Some rare SNPs were investigated in a case–control study among 971 children with malaria and 891 unmatched apparently healthy control school children and blood bank donors in a bid to identify novel ones that may be linked to malaria and TGF-ß and IL-10 levels." (PMID 24934404, 2014). "In addition, prior studies have shown that IL-10 blockade increases malaria-specific IFNγ cytokine production in filaria-coinfected individuals and in cord blood mononuclear cells from neonates born to mothers exposed to malaria." (PMID 24415936, 2014).